FASLG (Fas ligand)
Diseases named in the same sentence as FASLG in open-access papers (continued):
Sharing a sentence is not in itself a finding about the gene and the disease.
type 2 diabetes mellitus (7 papers, 2014 to 2022). A type of diabetes mellitus that is characterized by insulin resistance or desensitization and increased blood glucose levels. "Similar to Fas, Fas ligand (FasL) expression was increased in obese persons with type 2 diabetes." (PMID 24203314, 2014).
vitiligo (7 papers, 2019 to 2025). Generalized well circumscribed patches of leukoderma that are generally distributed over symmetric body locations and is due to autoimmune destruction of melanocytes. "The FAS polymorphisms (FAS‐1377A>G) and FASLG SNP rs78037977 are reported to be associated with higher vitiligo risk." (PMID 33200838, 2021). "FAS and FASLG polymorphisms are also critical members of vitiligo SNPs." (PMID 33200838, 2021). "Genome-wide association studies (GWAS) have identified approximately 50 vitiligo-susceptibility genes, including PTPN1, PTPN22, NLRP1, FASLG, and TYR." (PMID 40837363, 2025). "Other candidate loci for vitiligo in several ethnicities include FASLG, a member of the TNF superfamily, and GZMB, a protease, both of which point to a role of dysregulated apoptosis in vitiligo." (PMID 35643735, 2022). "Highly significant changes in the expression of T cell activation-related genes IFNG, FASLG, GZMA and IL21 and anti-inflammatory genes IL10 and TGFB1 were found in growing feathers of vitiligo-expressing Smyth chickens (P < 0.0001)." (PMID 38720888, 2024). "Furthermore, inflammatory factors and interleukin (IL) signaling pathway (IL4 and IL10), adaptive immune response (IFNG), and cell apoptosis (FASLG and TNF) also played critical roles in the clarification of the mechanisms of KBL on vitiligo." (PMID 31781265, 2019).
cholangiocarcinoma (6 papers, 2007 to 2025). A carcinoma that arises from the intrahepatic biliary tree (intrahepatic cholangiocarcinoma) or from the junction, or adjacent to the junction, of the right and left hepatic ducts (hilar cholangiocarcinoma). "Cholangiocarcinoma cells evade immune surveillance by obstructing Fas receptor (FasR) signaling or augmenting Fas ligand (FasL) expression to trigger apoptosis in T cells." (PMID 40070825, 2025).
head and neck squamous cell carcinoma (6 papers, 2017 to 2026). A squamous cell carcinoma that arises from any of the following anatomic sites: lip and oral cavity, nasal cavity, paranasal sinuses, pharynx, larynx, and salivary glands. "We next examined the CASP8 mutation status of FASLG expressing tumours in The Cancer Genome Atlas (TCGA) head and neck squamous cell carcinoma (HNSCC) dataset using cBioPortal." (PMID 37443405, 2023).
heart failure (6 papers, 2014 to 2024). Inability of the heart to pump blood at an adequate rate to meet tissue metabolic requirements. "These molecular events have been associated with the progression of this pathophysiology, via Fas (sFas), Fas ligand (sFas-L), TNFα (tumor necrosis factor α), and IL-6 (interleukin-6), which are negatively correlated with fractional shortening and result in heart failure." (PMID 34445422, 2021). "Furthermore, in a model of heart failure, macrophages were reported to induce cell apoptosis through secretion of Fas Ligand." (PMID 24632850, 2014). "Furthermore, oxidative stress may also activate NF-κB and initiate the transcription of numerous pro-apoptotic genes, which includes Bax, Fas and Fas ligand, inducing myocardial cell apoptosis and further promoting heart failure condition." (PMID 33339902, 2020).
HIV-1 infection (6 papers, 2007 to 2023). The type species of lentivirus and the etiologic agent of acquired immunodeficiency syndrome (AIDS). "However, expression of death receptors for Fas ligand and TWEAK (tumor necrosis factor–like weak inducer of apoptosis) were not affected by HIV-1 infection." (PMID 17907802, 2007).
liver failure (6 papers, 2010 to 2022). A liver disease characterized by the liver losing or has lost all of its function. "Immunohistochemical studies of explanted ALF livers revealed marked expansion of CD68+ macrophages and augmented Fas Ligand expression by KCs, hinting at the induction of macrophage-mediated hepatocyte apoptosis through Fas–FasL interactions as a pathogenic pathway in human liver failure." (PMID 23091461, 2012). "Although, experimental studies have demonstrated that Fas (sFas)/Fas-ligand (FasL) signalling system plays a key role in liver failure, its role is not yet known." (PMID 24976841, 2014).
lung adenocarcinoma (6 papers, 2013 to 2024). A carcinoma that arises from the lung and is characterized by the presence of malignant glandular epithelial cells. "CAFs isolated from lung adenocarcinomas and melanoma tumors were shown to process and present antigens, and directly interact with activated CD8+ T cells, thus inducing T cell death via PD-L2 and FAS ligand (FASL) engagement." (PMID 31428105, 2019).
myelodysplastic syndrome (6 papers, 2019 to 2024). A clonal hematopoietic disorder characterized by dysplasia and ineffective hematopoiesis in one or more of the hematopoietic cell lines. "In low-risk Myelodysplastic Neoplasms (MDS), increased activity of apoptosis-promoting factors such as tumor necrosis factor (TNFα) and pro-apoptotic Fas ligand (CD95L) have been described as possible pathomechanisms leading to impaired erythropoiesis." (PMID 38413410, 2024).
ovarian tumor (6 papers, 2005 to 2025). "The inhibition of the Fas/Fas ligand (FasL) apoptotic system maybe determines the growth of ovarian tumor." (PMID 21617769, 2011).
pancreatic adenocarcinoma (6 papers, 2013 to 2025). "In addition, D. nobile extracts down regulated the expression level of decoy receptor-3 and synergized with Fas ligand to bring about apoptotic cell death in pancreatic adenocarcinoma cells." (PMID 37393306, 2023). "Conversely, in the cases of RIPK3 and FASLG, between the CNV mutation rates and the expression levels, showed a negative correlation in THYM and pancreatic adenocarcinoma (PAAD)." (PMID 37000317, 2023).
pneumonia (6 papers, 2012 to 2025). An acute, acute and chronic, or chronic inflammation focally or diffusely affecting the lung parenchyma, caused by an infection in one or both of the lungs (by bacteria, viruses, fungi, or mycoplasma.). "We also found one variant in FASLG (p.R198W) in two sisters (patients 27 and 28) with recurrent pneumonias and low B cells." (PMID 27379089, 2016). "Research indicates that the BL13 acupoint modulates pneumonia by targeting multiple genes, such as FCER2, IL4R, FASLG, and others, to modulate cytokine signaling in the immune system." (PMID 40098935, 2025).
renal cell carcinoma (6 papers, 2000 to 2021). "In sharp contrast, high FASLG expression in renal cell carcinoma (P = 0.04) and uveal melanoma (P = 0.000059) was associated with significantly worse prognosis." (PMID 29123081, 2017).
silicosis (6 papers, 2010 to 2025). Silicosis is a respiratory disease caused by breathing in (inhaling) silica dust. "One of the key players in the immunological effects of silicosis is the Fas/Fas ligand (FasL) system, which includes soluble Fas (sFas)." (PMID 40438828, 2025). "Fas ligand-deficient GLD mice instilled with silica do not develop silicosis." (PMID 38515835, 2024). "AM apoptosis also contributes to the pathogenesis of TB and silicosis, with increased expression of cellular apoptosis receptors (FAS) and their ligands (FASLG and TNFα), promoting the recruitment of inflammatory cells." (PMID 40531729, 2025).
triple-negative breast carcinoma (6 papers, 2018 to 2024). An invasive breast carcinoma which is negative for expression of estrogen receptor (ER), progesterone receptor (PR), and human epidermal growth factor receptor 2 (HER2). "Furthermore, Withaferin A induces the mitochondria and Fas ligand–Fas-mediated intrinsic apoptotic pathway in triple-negative breast cancer cells by up-expressing miR-181c-5p levels." (PMID 36676955, 2022).
acute kidney injury (5 papers, 2015 to 2023). Sudden and sustained deterioration of the kidney function characterized by decreased glomerular filtration rate, increased serum creatinine or oliguria. "We genotyped 367 SNPs in 45 genes of the Fas/Fas ligand pathway to identify associations between SNPs in Fas pathway genes and the development of AKI by day 2 after enrollment in FACTT, adapting Acute Kidney Injury Network (AKIN) criteria." (PMID 26477820, 2015).
Alzheimer disease (5 papers, 2015 to 2024). A progressive, neurodegenerative disease characterized by loss of function and death of nerve cells in several areas of the brain leading to loss of cognitive function such as memory and language. "Additionally, a direct injury to neurons by Th17 cells through the Fas/ Fas Ligand (FasL) pathway was reported in a mouse Alzheimer’s disease model." (PMID 34360808, 2021).
astrocytoma (5 papers, 2007 to 2024). "Additionally, astrocytes have been shown to directly induce T cell apoptosis via cell-cell contacts; astrocytoma derived astrocytes express Fas ligand (FasL) which interacts with Fas expressing cells, such as T cells, to induce cytolysis." (PMID 23596394, 2013).
autoimmune hepatitis (5 papers, 2012 to 2024). Hepatitis caused by autoantibodies. "For instance, Lian and coworkers demonstrated that CDCA, as a FXR agonist, exerts an anti-apoptotic role in a concanavalin A induced autoimmune hepatitis mouse model via downregulating Fas/Fas ligand, TRAIL, and caspase-3." (PMID 30558117, 2018).
chronic periodontitis (5 papers, 2006 to 2023). A chronic inflammatory process that affects the tissues that surround and support the teeth. "Soluble FasL was found to be higher in gingival crevicular fluid obtained from patients with chronic periodontitis than in healthy controls and the jawbone of human foetuses revealed the expression of Fas on both osteoblasts and osteoclasts and of Fas ligand on osteoblasts." (PMID 36384160, 2023).
renal carcinoma (5 papers, 2019 to 2025). A carcinoma arising from the epithelium of the renal parenchyma or the renal pelvis. "Another overexpressed factor on the tumor-associated vasculature that has been implicated in TILs exclusion is Fas ligand (FasL), produced by murine and human tumors, like ovarian, colon, prostate, breast, bladder, and renal cancer." (PMID 37284199, 2023). "Galectin-1 inhibits the secretion process of cytotoxic cells and promotes renal cancer cells to migrate through affecting Fas–Fas ligand." (PMID 41210885, 2025). "All three genes, CFLAR, FAS, and FASLG, were significantly higher expressed in ccRCC compared with the other two renal cancer types." (PMID 31097685, 2019). "Moreover, analysis of public data on the expression levels of c-FLIP (CFLAR), CD95 (FAS/TNFRSF6), and CD95L (FASLG) revealed significantly higher expression of these three genes in ccRCC compared with other renal cancers." (PMID 31097685, 2019). "For example, the apoptosis inducer Fas ligand (FAS-L) is highly expressed in the tumor vasculature of multiple tumor types including ovarian, colon, prostate, breast, bladder, and renal cancer, which substantially reduces the number of CD8+T cell infiltration into tumors." (PMID 33613544, 2020).
Acute hepatitis (4 papers, 2016 to 2022). Acute hepatic injury resulting from inflammation typically accompanied by increased serum alanine transaminase activity. "It has been further found that the cytokine production depends on the interaction between lymphocytes and macrophages and that Fas ligand (FasL) expression on liver natural killer T cells (NKT) plays a role in the pathogenesis of this model for acute hepatitis." (PMID 27916939, 2016).
anemia (4 papers, 2018 to 2025). A reduction in the number of red blood cells, the amount of hemoglobin, and/or the volume of packed red blood cells. "As a possible molecular pathomechanism for anemia in low-risk MDS, a pro-apoptotic niche with increased activity of apoptosis-promoting factors such as tumor necrosis factor (TNFα) and pro-apoptotic Fas ligand (CD95L) have been proposed." (PMID 38413410, 2024).
autoimmune thyroiditis (4 papers, 2014 to 2024). "Specifically, FASLG was predominantly enriched in KEGG pathways associated with Parkinson's disease, autoimmune thyroid disease, graft‐versus‐host disease, antigen processing and presentation and allograft rejection." (PMID 39031474, 2024).
celiac disease (4 papers, 2014 to 2025). An autoimmune genetic disorder with an unknown pattern of inheritance that primarily affects the digestive tract. "In celiac disease (CeD), interleukin 15 (IL-15) affects the epithelial barrier by acting on intraepithelial lymphocytes, promoting interferon γ (IFN-γ) production and inducing strong cytotoxic activity as well as eliciting apoptotic death of enterocytes by the Fas/Fas ligand system." (PMID 39937025, 2025).
fatty liver disease (4 papers, 2014 to 2022). A reversible condition wherein large vacuoles of triglyceride fat accumulate in liver cells via the process of steatosis. "IL-22 was found to enhance liver regeneration and protect the liver against fatty liver disease, as well as against ethanol-, concanavalin A-, carbon tetrachloride-, and Fas ligand-induced liver injury." (PMID 24799907, 2014).
Hashimoto thyroiditis (4 papers, 2019 to 2023). An autoimmune disorder caused by the production of autoantibodies against thyroid tissue. "Fas and Fas-ligand are expressed in the follicular cells in Hashimoto’s thyroiditis, which contributes to thyroid destruction." (PMID 38011178, 2023). "Thyroid cells, both Graves’ disease and Hashimoto’s disease, showed a strong expression of Fas ligand together with a receptor for Fas." (PMID 33193078, 2020).
lung diseases (4 papers, 2021 to 2024). "The FASLG-FAS pathway is a representative system of apoptosis signaling ligand-receptor molecules that may play an important role in the pathogenesis of fibrosing lung diseases." (PMID 37653115, 2023).
promyelocytic leukemia (4 papers, 2015 to 2020). "Arsenic has been linked to FASLG protein expression, mainly in in vitro studies of the cancer drug arsenic trioxide, which is currently used for treatment of acute promyelocytic leukemia." (PMID 33381488, 2020).
ulcerative colitis (4 papers, 2014 to 2025). An inflammatory bowel disease involving the mucosal surface of the large intestine and rectum. "Additionally, FASLG seems also to play a basic role in this sub-phenotype and has been documented in the attenuation of apoptosis response to Fas-ligand in active ulcerative colitis." (PMID 31249629, 2019).
autoimmune thrombocytopenia (3 papers, 2014 to 2022). An autoimmune form of thrombocytopenia. "In Fas ligand (FasL) deficient mice, knockout of TRAIL exacerbates the FasL knockout phenotype, leading to extreme lymphoproliferation and fatal autoimmune thrombocytopenia, indicating that the TRAIL-R system partially functions as gatekeeper in absence of Fas signaling." (PMID 31114586, 2019).
bacteremia (3 papers, 2012 to 2023). "In the early stages of the T-cell dependent host response to pneumococci reduced Fas ligand mediated T-cell apoptosis was associated with decreased bacterial clearance in the lung and increased bacteremia." (PMID 22829769, 2012).
co-infection (3 papers, 2015 to 2024). "qRT-PCR also demonstrated co-infection significantly increased expressions of CASP2, CASP3, BC2L11, FASLG, and TNFRSF8." (PMID 25906258, 2015). "Notably, Several genes, such as FASLG, MX1, and GBP, exhibit notable upregulation under co-infection conditions, suggesting a heightened oxidative stress response or immune activation." (PMID 39770656, 2024).
diffuse large B-cell lymphoma (3 papers, 2019 to 2023). "The StemnessScores in both RNAss and DNAss were negatively correlated with FASLG and MLKL expressions in cancers such as Lymphoid Neoplasm Diffuse Large B-cell Lymphoma (DLBC), GBM, KICH, and LUSC." (PMID 37000317, 2023).
E. coli infection (3 papers, 2018 to 2023). "Other factors sporadically present were the Pla protease from Yersinia pestis, which prevents host cell apoptosis and inflammation by degrading Fas ligand (FasL), and the Cah autotransporter associated with enterohemorrhagic E. coli infections." (PMID 37707451, 2023).
intervertebral disc degeneration (3 papers, 2018 to 2024). "It is known that Fas ligand (FasL) is involved in the development of intervertebral disc degeneration (IDD)." (PMID 32143617, 2020). "More critically, MAGI2-AS3 was revealed to be downregulated in patients with intervertebral disc degeneration, whereas elevated levels of MAGI2-AS3 suppressed Fas ligand expression and mediated the nucleus pulposus cells." (PMID 38907263, 2024).
pancreatic ductal adenocarcinoma (3 papers, 2016 to 2021). An infiltrating adenocarcinoma that arises from the epithelial cells of the pancreas. "Another possible hypothesis might be the production of lymphocyte-apoptosis inducers such as Fas-Ligand, by pancreatic ductal adenocarcinoma." (PMID 27782813, 2016).
polymyositis (3 papers, 2023 to 2025). A rare idiopathic inflammatory myopathy characterized by symmetric proximal muscle weakness and elevated muscle enzymes. "In polymyositis, the death of myofibroblasts is moderated by Fas/Fas ligand-dependent necroptosis, and the inhibition of necroptosis therefore can improve muscle weakness caused by myositis." (PMID 39858052, 2025).
psoriasis (3 papers, 2016 to 2025). An autoimmune condition characterized by red, well-delineated plaques with silvery scales that are usually on the extensor surfaces and scalp. "Recently, the largest meta-analysis of GWAS for psoriasis has identified 16 novel genetic loci for psoriasis, including CHUK on chromosome 10q24.31, FASLG on chromosome 1q24.3 and IKBKE on chromosome 1q32.1, which are associated with the NF-κB signaling pathway." (PMID 29232931, 2017).
renal fibrosis (3 papers, 2022 to 2024). A final common manifestation of a wide variety of chronic kidney diseases characterized by glomerulosclerosis and tubulointerstitial fibrosis. "There was no variation in the severity or extent of renal fibrosis after UUO when β-catenin depletion occurred, however, it enhanced the survival of interstitial fibroblasts through the MMP-7 (matrix metalloproteinases-7)/FasL (Fas ligand) pathway." (PMID 38260142, 2023).
retinal degeneration (3 papers, 2015 to 2024). Degeneration of the retina. "Apoptosis of photoreceptor cells is a common feature of retinal degeneration, and a variety of stimuli, such as tumor necrosis factor (TNF), Fas ligands (FasL), mitochondria, and ER stress, can lead to cell death." (PMID 26137316, 2015).
rhabdomyosarcoma (3 papers, 2021 to 2022). A rare aggressive malignant mesenchymal neoplasm arising from skeletal muscle. "Regarding the mode of action, baicalin blocked the expression of mRNA and polymerase in the early stages of infection by decreasing the expressions of Fas ligand (FasL) and caspase-3 that inhibit the Enterovirus A71 apoptosis in Rhabdomyosarcoma cells." (PMID 34200456, 2021).
schizophrenia (3 papers, 2021 to 2025). A major psychotic disorder characterized by abnormalities in the perception or expression of reality. "FASLG acts as a marker of apoptosis, and increased apoptotic signaling occurs at the onset of schizophrenia and is associated with treatment progression." (PMID 37383091, 2023). "Part of these data are presented as an abstract [Soluble Fas ligand (sFasL) as a predictor of the reduction in general psychopathology in schizophrenia after antipsychotic treatment] at the 24th European Congress of Psychiatry, Madrid, Spain, 2016." (PMID 41010622, 2025). "A member of TNF family, Fas ligand (FasL), participates in apoptosis, but its connection with treatment-resistant schizophrenia is unknown." (PMID 41010622, 2025).